HNF4A (hepatocyte nuclear factor 4 alpha)
Diseases named in the same sentence as HNF4A in open-access papers (continued):
Sharing a sentence is not in itself a finding about the gene and the disease.
infectious disease (1 paper, 2025). A disorder directly resulting from the presence and activity of a microbial, viral, or parasitic agent in humans. "Given its protective role across bacterial, viral, and coinfection models, Hnf4α represents a promising therapeutic target for infectious disease management in aquaculture." (PMID 40920830, 2025). "Given the global burden of infectious diseases in aquaculture, Hnf4α represents a promising therapeutic target for enhancing host resilience against complex pathogen challenges." (PMID 40920830, 2025).
inflammation (1 paper, 2025). Aberrant reaction of the microcirculation characterized by movement of fluid and leukocytes from the blood into extravascular tissues. "KC-mediated hepatic inflammation, most notably IL-1β, led to the transcriptional inhibition of A1AT by HNF4α." (PMID 39939782, 2025).
intestinal diseases (1 paper, 2023). "The microbiota-HNF4α relationship may have important implications for understanding and addressing human intestinal diseases." (PMID 37635981, 2023).
retinopathy (1 paper, 2024). "The frequency of retinopathy was low, and the presence of microalbuminuria was 0% in ABCC8‐MODY and KCNJ11‐MODY, while microalbuminuria ranged from 1.8% in HNF4A‐MODY and HNF1A‐MODY to 16.7% (1 out of 6 individuals) in KLF11‐MODY." (PMID 39511990, 2024).
HNF4A also shares sentences with these, for which no sentence is quoted: maturity-onset diabetes of the young (22 papers); Hyperinsulinemia (11); rectal adenocarcinoma (4); alcoholic liver diseases (3); alcoholism (3); chronic hepatitis B (3); esophageal cancer (3); schizophrenia (3); asthma (2); breast tumor (2); cardiomyopathy (2); cystic fibrosis (2); Immunodeficiency (2); kidney damage (2); myocardial infarction (2); papillary adenocarcinoma (2); RCAD) syndrome (2); renal Fanconi syndrome (2); acute myeloid leukemia (1); acute-on-chronic liver failure (1); Alström’s syndrome (1); amyotrophic lateral sclerosis (1); atransferrinemia (1); autism spectrum disorder (1); autoimmune disorders (1); autoimmune hepatitis (1); autosomal dominant polycystic kidney disease (1); B-Cell CLL (1); bone osteosarcoma (1); celiac disease (1).
A further 73 diseases each share a sentence with HNF4A in 1 paper.